CYP2A6 (cytochrome P450 family 2 subfamily A member 6)
Diseases named in the same sentence as CYP2A6 in open-access papers (continued):
Sharing a sentence is not in itself a finding about the gene and the disease.
lung carcinoma (continued). "In addition, lung cancer might arise due to occupational carcinogen exposure, such as organic dust and silica dust, which may confound the association between CYP2A6 polymorphism and lung cancer risk." (PMID 32547353, 2020). "Therefore, the phenotyping of CYP2A6 activity could be more appropriate for estimating lung cancer risk related to nicotine metabolism." (PMID 31430927, 2019). "Clinically, genetic variation in CYP2A6 may contribute to lung cancer risk." (PMID 30148168, 2018). "Thus it is reasonable to hypothesize that CYP2A6 activity may be related to the susceptibility of developing lung cancer among smokers." (PMID 29724170, 2018). "However, the higher risk of lung cancer in Native Hawaiians is inconsistent with their smoking intensity and nicotine metabolism rate, measured by CYP2A6 activity (the ratio of total trans-3′-hydroxycotinine over total cotinine), which is intermediate between that of whites and Japanese Americans." (PMID 30139389, 2018). "Indeed, when Japanese Americans, a group with a >35% frequency of carrying at least one copy of the CYP2A6 gene deletion (*4), were removed from our analysis, the association for higher CYP2A6 activity with lung cancer was statistically significant in the remaining four racial/ethnic groups." (PMID 28542511, 2017). "In addition to playing a primary role in the metabolism of nicotine, in turn influencing many smoking behaviors, including quitting smoking, as well as tobacco-related diseases such as lung cancer risk, the CYP2A6 enzyme also metabolizes several other clinically relevant substrates." (PMID 29194389, 2017). "The minor alleles of these CYP2A6 SNPs were associated with reduced nicotine metabolism, smoking heaviness and lung cancer risk in a mechanistically interpretable fashion (reduced nicotine metabolism rate reduces cigarette consumption reduces lung cancer risk)." (PMID 26132489, 2015). "Methoxsalen, a natural coumarin which is a well-known medication for psoriasis, functions as a potent therapeutic agent for lung cancer through selective inhibition of CYP2A6 and CYP2A13." (PMID 41249771, 2025). "Due to extrahepatic expression, it has gained less attention than CYP2A6, despite the fact that it plays a significant role in toxicant-induced pulmonary lesions and, therefore, lung cancer." (PMID 34830188, 2021). "The lung cancer studies described are presented to delineate the importance of CYP2A6 to nicotine and tobacco exposure." (PMID 33932402, 2021). "Studies of CYP2A6 inhibition demonstrated a role for the enzyme in the occurrence of lung cancer and hence have directed the interest in CYP2A6 as a target for cancer prevention." (PMID 29724170, 2018). "Our study, in the setting of patients with lung cancer demonstrates that the frequency of slow metabolizer CYP2A6*2 and CYP2A6*9 are poor in the studied Egyptian population; who are non-smokers." (PMID 29724170, 2018). "Associations of biomarkers of nicotine uptake (TNE) and nicotine metabolism (CYP2A6 activity) with lung cancer incidence (92 cases)." (PMID 28542511, 2017). "We found that higher CYP2A6 activity and TNE was associated with increased lung cancer risk after adjusting for age, sex, race/ethnicity, body mass index, smoking duration, and urinary creatinine (p’s = 0.002)." (PMID 28542511, 2017). "Thus, measuring CYP2A6 activity may improve lung cancer risk prediction in smokers." (PMID 28542511, 2017). "Although previous studies have demonstrated the upregulation of CYP2A6 protein and mRNA in human lung cancer and colorectal cancer, this is the first report on CYP2A6 gene amplification and overexpression in bladder cancer." (PMID 27902773, 2016). "Nicotine metabolism by cytochrome P450 2A6 (CYP2A6) varies across ethnicity and race, which is indicated to be related to smoking behavior and lung cancer risk." (PMID 25915206, 2015).
lung carcinoma (continued). "We confirmed the major role that CYP2A6 plays in nicotine metabolism, and made novel findings with respect to genome-wide significance and associations with CPD, abstinence and lung cancer risk." (PMID 26132489, 2015). "CYP2A6*4/*4 (whole gene deletion) was found in only one female patient in this subgroup, whereas among 387 lung cancer patients, CYP2A6*4/*4 was detected in seven patients (1.8%) with lung adenocarcinoma." (PMID 24040073, 2013). "Additionally, these genes could be contributing to lung cancer risk directly through altered nitrosamine pharmacology—the CYP2A6 enzyme metabolically activates tobacco specific nitrosamines (TSNA) and the nicotinic receptors are high-affinity binding sites for nitrosamines." (PMID 23591849, 2013). "Previously we found that variation in CYP2A6 and CHRNA5-CHRNA3-CHRNB4 combined to increase lung cancer risk in a case-control study in European American ever-smokers (n = 860)." (PMID 23591849, 2013). "Owing to the contribution of these genes to nicotine pharmacology, CYP2A6 and CHRNA5-A3-B4 increase lung cancer risk indirectly through increased cigarette consumption and thus increased carcinogen exposure." (PMID 23591849, 2013). "Our argument is supported by the fact that a similar approach using a selective CYP2A6 inhibitor is being considered to treat nicotine dependence and to prevent tobacco/nicotine-mediated lung cancer." (PMID 22530035, 2012). "Females also metabolize nicotine more efficiently than males, largely due to higher estrogen levels that enhance the activity of the CYP2A6 enzyme—an effect that may impact lung cancer development in smokers." (PMID 40890819, 2025). "However, it is possible that smoking behavior is the primary cause of lung cancer, with genetic mutations in CYP1A2 and CYP2A6 being secondary factors in its development." (PMID 39457450, 2024). "Eighteen studies reported a link between CYP2A6 and lung cancer." (PMID 39457450, 2024). "Taken together, these lung cancer studies of CYP2A6 genotype, P450 2A6 metabolism, and total nicotine equivalents confirm the relationship of CYP2A6 genotype to lung cancer risk in individual smokers independent of their racial/ethnic identity." (PMID 33932402, 2021). "The protective effect of CYP2A6 genotype on lung cancer risk was no longer significant when adjusted for total nicotine equivalents, since nicotine consumption was mediating this association." (PMID 33932402, 2021). "The first studies to demonstrate this were carried out in populations with a high prevalence of CYP2A6 nonfunctional variants, but now there is good evidence that CYP2A6 genotype contributes to a smoker's lung cancer risk in a number of different populations." (PMID 33932402, 2021). "Many studies, including the first to report an association between CYP2A6 genotype and lung cancer, hypothesized that decreased activation of NNK in smokers with decreased P450 2A6 activity protects smokers from lung cancer risk." (PMID 33932402, 2021). "A large collaborative study provided strong evidence for the contribution of CYP2A6-mediated nicotine metabolism to lung cancer risk in a non-Asian population." (PMID 33932402, 2021). "Therefore, the phenotypes of CYP2A6*4 and CYP2A6*5 protect the carriers against lung cancer or other cancers." (PMID 33192522, 2020). "In this study, 5 out of 7 lung cancer cases (71.4%) with CYP2A6 slow metabolizer were non- smokers." (PMID 29724170, 2018). "Liu & colleagues suggested that decreasing or abolishing the activity of the CYP2A6 by means of specific inhibitors might prevent the frequency of occurrence of tobacco-induced lung cancer in smokers only." (PMID 29724170, 2018). "There was no statistical significant association between risk of lung cancer, smoking habits, heaviness of smoking and the different polymorphisms of CYP2A6 genotypes." (PMID 29724170, 2018).
lung carcinoma (continued). "The majority of studies that have been conducted have found that CYP2A6 variants that result in reduced or no enzymatic activity are inversely associated with lung cancer risk." (PMID 28542511, 2017). "CYP2A6 minor alleles were associated with reduced NMR, CPD, and lung cancer risk." (PMID 26132489, 2015). "Genome-wide association studies have identified single nucleotide polymorphisms (SNPs) as risk factors for nicotine dependence and lung cancer in genes encoding nAChR subunits (CHRNB3-CHRNA6 and CHRNB4-CHRNA3-CHRNA5 clusters), and in nicotine-metabolizing enzymes (CYP2A6 and CYP2B6)." (PMID 26623516, 2015). "Combined analyses of concurrent variation in CYP2B6, CYP2A6 and CHRNA5-A3-B4 appeared to stratify ever-smokers by lung cancer risk supporting an important role for variation in both nicotine/nitrosamine pharmacokinetic and pharmacodynamic pathways to the risk for lung cancer among smokers." (PMID 23591849, 2013). "We have reported that variation in the nicotine and nitrosamine metabolizing gene, CYP2A6, and the nicotinic receptor subunit gene cluster, CHRNA5-CHRNA3-CHRNB4 (CHRNA5-A3-B4), combined to increase cigarette consumption and lung cancer risk among European American cigarette smokers." (PMID 23591849, 2013). "Cytochrome P450 2A6 (CYP2A6) is known to metabolize nicotine, the major constituent of tobacco, leading to the production of toxic metabolites and induction of oxidative stress that result in liver damage and lung cancer." (PMID 22530035, 2012). "In this large population-based case-control study of lung cancer we have observed that EPHX1, CYP1A1, CYP1B1 and CYP2A6 genes may play a role in lung cancer susceptibility." (PMID 19479063, 2009). "The absence of the CYP2A6 enzyme could reduce the risk of lung cancer because the activation of procarcinogens would be decreased." (PMID 33192522, 2020). "It seemed probable that genetic polymorphism in CYP2A6 causing a lack of or reduced activity might result in lowering tobacco-induced lung cancer risk, by decreased smoking." (PMID 29724170, 2018). "Thus knowing that CYP2A6 activity affects genetic suscebility to tobacco- induced lung cancer, individuals possessing the CYP2A6*2 and/or CYP2A6*9, but not the CYP2A6*1A allele would be expected to be at lower risk for lung cancer." (PMID 29724170, 2018). "Our findings did not suggest any association between CYP2A6 genotypes and risk of lung cancer." (PMID 29724170, 2018). "However, this study was comprised of Chinese, a population with a relatively high frequency of the CYP2A6 deletion (*4) and the association of lung cancer risk with the CYP2A6 genotype was no longer statistically significant when adjusted for TNE." (PMID 28542511, 2017). "As slower nicotine metabolism, due to less CYP2A6 enzyme activity, is associated with smoking fewer CPD, and lower smoking intensity, CYP2A6 activity variation may indirectly influence lung cancer risk through lowering smoking quantity and procarcinogen exposure." (PMID 29194389, 2017). "In the present lung cancer analysis, when CYP2A6 activity was adjusted for, TNE was no longer associated with risk, suggesting that the enzymatic activity ratio more accurately captures a smoker’s long-term tobacco carcinogens exposure than does TNE, which only reflects short-term exposure." (PMID 28542511, 2017). "Furthermore, additional animal studies modulating the expression and/or activity level of nitrosamine metabolizing enzymes, such as CYP2A and CYP2B, would provide valuable insight into the biological mechanism behind our observed differences in lung cancer risk by CYP2B6 and CYP2A6 gene variants." (PMID 23591849, 2013). "Previous reports have indicated that the deletion of CYP2A6 (CYP2A6*4C) may reduce the risk of lung cancer, suggesting that people with CYP2A6*4C may not activate tobacco nitrosamines from smoking." (PMID 23983642, 2013). "Whether CYP1A2 and CYP2A6 are genetically linked to lung cancer in nonsmokers remains unclear." (PMID 39457450, 2024).
lung carcinoma (continued). "Therefore, the true relationship between CYP2A6 polymorphism and risk of lung cancer in current-smokers and never-smokers could not be tested in these six studies." (PMID 32547353, 2020). "Thus, in individuals with the inactive CYP2A6 genotype, the CYP2A6 enzyme might not affect metabolic activation of N-nitrosamines and subsequently reduce the risk of lung cancer." (PMID 32547353, 2020). "Thus, when the original studies included both smokers and non-smokers, the association between the CYP2A6 polymorphism genotype and risk of lung cancer may have been attenuated." (PMID 32547353, 2020). "However, the CYP2A6 enzyme can act directly via metabolically activating procarcinogenic tobacco-specific nitrosamines NNN and NNK via α-hydroxylation suggesting that slower activation may also lower lung cancer risk." (PMID 29194389, 2017). "In particular the polymorphism CYP2A6 rs1801272 selected for this study, which causes an amino acid change from Leu to His, has been object of dispute: studies found a protective association with lung cancer and amount of cigarette smoke which has not been consistently replicated." (PMID 19479063, 2009). "Involvement of highly significant DEGs including SLCO1A2, OLFM4, RTKN2, CYP1A1, and MUC5AC plays a key role in rheumatoid arthritis development.Highly significant DEGs including OLFM4, RTKN2, CYP1A1, MUC5AC, CYP2A6, PCK1, and PITX1 have been reported to encourage the development of lung cancer." (PMID 38137330, 2023). "The significantly lower dose of carcinogens received by smokers who carry variant CYP2A6 alleles, not decreased bioactivation of NNK, is likely the far greater contributor to their lower lung cancer risk." (PMID 33932402, 2021). "In addition to CYP2A6, CYP2A13 also plays a significant role in smoking-induced lung cancer due to its involvement in metabolising tobacco-specific nitrosamines." (PMID 33809117, 2021). "There was no statistical significant difference in the CYP2A6 genotypes in different stages of lung cancer." (PMID 29724170, 2018). "S1 Fig presents density distribution plots for TNE and the CYP2A6 activity ratio both without and with log-transformation for the overall cohort and by lung cancer case-control status." (PMID 28542511, 2017). "When adjusting for CYP2A6 activity, a biomarker found to influence smoking dose, the association with TNE was no longer statistically significant (lung cancer HR per unit increase in log-TNE = 1.30; 95% CI: 0.85–1.99)." (PMID 28542511, 2017). "Significant CYP2A6 SNP associations with CPD, with prospective abstinence by pharmacotherapy, and with lung cancer were post-hoc and were not replicated in this study." (PMID 26132489, 2015). "In addition, CYP2A6 activates multiple tobacco procarcinogens including 4-(methylnitrosamino)-1-(3-pyridyl)-1-butanone (NNK), leading to liver damage and lung cancer." (PMID 22530035, 2012). "In contrast, the association between TNE and lung cancer risk was of borderline statistical significance when adjusted for CPD (HR = 1.53; p = 0.06) and not statistically significant when further adjusted for CYP2A6 activity (HR = 1.30; p = 0.22)." (PMID 28542511, 2017). "Based on this analysis and additional studies cited, CYP2A6 SNPs account for large fractions of the variance of the NMR, smaller fractions of the variance of cigarette consumption, and influence risk for lung cancer, but do not account for other nicotine dependence factors." (PMID 26132489, 2015). "Two genotypes were detected in CYP2A6*9; heterozygote AC and homozygote CC.AC genotype was found in 4 cases in control group; 3 males and 1 female, all cases were non-smokers and 6 cases in lung cancer group; 4 males and 2 females from which 2 males were smokers > 20 pack-year." (PMID 29724170, 2018). "In lung cancer, TMB was significantly lower in the absence of normal CYP2A6 (deletion type) than in the retained type, regardless of the smoking status of the patient." (PMID 41272073, 2025).
lung carcinoma (continued). "Since the level of CYP2A13, but not CYP2A6, was correlated with lung microsomal NNK metabolic activity, it was speculated that people with relatively high levels of CYP2A13 expression are likely to have an increased risk of developing smoking-related lung cancer." (PMID 34830188, 2021). "Those who developed lung cancer during study follow-up presented with a slightly higher TNE and CYP2A6 activity levels than subjects who did not become a case during the same period of time." (PMID 28542511, 2017).